STAT3 (signal transducer and activator of transcription 3)
Diseases named in the same sentence as STAT3 in open-access papers (continued):
Sharing a sentence is not in itself a finding about the gene and the disease.
cancer (continued). "Both STAT3 and NF-κB participate in the EMT of cancer cells, which aligns with our findings that CIB-6 suppresses the proliferation of HCC cells in vitro and in vivo, and inhibits EMT-mediated HCC migration." (PMID 33805945, 2021). "On the other hand, cancer pathologies in lung tissue also switch on the transcription of STAT3, leading to the upregulated expression of ACE2 in cancer cells." (PMID 34501332, 2021). "To evaluate the process of cancer development in BxPC-3 CM-treated C2C12 cells, we analyzed STAT3, Akt, and FoxO4 phosphorylation by Western blot analysis." (PMID 33802674, 2021). "Numerous studies have reported that UA regulates the apoptosis, proliferation, metastasis, and cell cycle of different cancer cells through several signaling pathways, including Akt/PI3K, NF-Κβ, and STAT3." (PMID 34768915, 2021). "Since STAT3, LC3B and PKCα are involved in cancer cell migration, autophagy and apoptosis, Western blot analysis of their protein levels in cells was performed." (PMID 34829932, 2021). "Activation of inflammatory or innate immune signaling in cancer, such as IL-6/JAK/STAT3 axis, NF-κB, and interferon signaling, can promote tumor cell survival." (PMID 34071428, 2021). "STAT3 is a part of the STAT family of transcription-factors and plays an important role in cancer-related inflammation." (PMID 33804548, 2021). "HIF-1α, STAT3, and CBP/p300 are known as transcriptional complex components that regulate the response to hypoxia in cancer." (PMID 34692527, 2021). "By promoting the activation of STAT3, TRIMs indirectly induce STAT3-target genes, such as MMP-2, MMP-9 and the vascular endothelial derived growth factor (VEGF), thus promoting cancer cell migration and invasion." (PMID 33673719, 2021). "At present, clinical trials are underway to target the activities of iNOS Arg1 and STAT3, metabolism through CD36, transport through CXCR2, and other mechanisms for different types of cancer." (PMID 34447750, 2021). "Another study showed that IL-6/JAK/STAT3 and TGF-β/SMAD pathways are required for the epithelial–mesenchymal transition in the early stages of cancer." (PMID 34771727, 2021). "Collectively, matrine targeted Src, inhibited its kinase activity, and down-regulated its downstream MAPK/ERK, JAK2/STAT3, and PI3K/Akt phosphorylation signaling pathways to inhibit the proliferation of cancer cells." (PMID 34642304, 2021). "The phosphorylation levels of MAPK/ERK, JAK2/STAT3, and PI3K/Akt signaling pathways in cancer cells were examined, respectively." (PMID 34642304, 2021). "Accumulating evidence shows that STAT3, MEK1, and AKT are frequently dysregulated in cisplatin-resistant cancer." (PMID 34321456, 2021). "Signal transducer and activator of transcription 3 (STAT3) plays a critical role in the formation and growth of human cancer." (PMID 34684783, 2021). "Several oncogenic targets of STAT3 have been recently identified such as c-myc, c-Jun, PLK-1, Pim1/2, Bcl-2, VEGF, bFGF, and Cten, and inhibitors of STAT3 have been developed for cancer prevention and treatment." (PMID 33435349, 2021). "Thus, targeting Stat3 may improve the efficacy of cancer chemotherapy." (PMID 34766149, 2021).
cancer (continued). "The cancer-related signaling pathways such as PI3K/AKT, ERK1/2, and STAT3 were analyzed using Western blotting." (PMID 33458757, 2021). "In cancer cells, S727 phosphorylation has been observed during the canonical STAT3 activation, where it may have a role in enhancing the transcriptional activity of STAT3, for example by recruiting cofactors, such as the histone acetyltransferase p300/CBP or by promoting the homodimer formation." (PMID 34642818, 2021). "Reciprocal cross talk between the STAT3 and EGFR pathways is a key molecular mechanism leading to resistance in cancer cells." (PMID 33259114, 2021). "The STAT3 signaling pathway has been reported to be involved in EMT induction and cancer metastasis in a variety of cancer types, including HCC." (PMID 35008530, 2021). "STAT3 has been found to be involved in promoting HCC development and malignant and cancer stemness characteristics." (PMID 33669204, 2021). "Based on previous researches, miR-98-5p is available to regulate cancer development through various target genes, like XIAP, BZW1, STAT3, IGF1 and so on." (PMID 34895048, 2021). "Therefore, miR-93-5-p may target STAT3 and suppress cancer cell invasion and migration in SCLC." (PMID 33535997, 2021). "Signal transducer and activator of transcription 3 (STAT3) and cyclooxygenase 2 (COX2)/PGE2 play a carcinogenic role in a variety of malignant tumors, which participate in the generation, maturation and accumulation of MDSCs." (PMID 34404434, 2021). "In summary, there is strong experimental evidence supporting the role of the transcription factor STAT3 as the main mediator of EMP induction by IL-6 and OSM in cancer." (PMID 34361105, 2021). "Several of the transcription factors that interact with Ref-1 have a profound impact on metabolic reprogramming in cancer, including HIF1-α, STAT3, and NRF2 (nuclear factor erythroid 2-related factor 2)." (PMID 34376225, 2021). "On the other hand, the link between STAT3 and IL6 has been reported in inflammation and cancer studies." (PMID 33672392, 2021). "Unfortunately, two promising phase III clinical trials with inhibitors of JAK/STAT3 (i.e. the JAK1/JAK2 inhibitor ruxolitinib and the STAT3 inhibitor napabucasin), the leading effector pathway of LIF stimulation in cancer cells, were stopped due to futility." (PMID 33630157, 2021). "Molecularly Signal Transducer and Activator Of Transcription 3 (STAT3)-phosphorylation and hexokinase 2-expression were reduced in human cancer cells treated with CM from IL-17RB OE PSCs." (PMID 34771503, 2021). "Among these pathways, STAT3 is crucial for activating the MMP9 gene and cancer stem phenotype in the 3D tumoroid model." (PMID 33562088, 2021). "For example, JQ1 and SAHA as co-treatments strengthened the anti-cancer efficacy of SAHA by preventing the SAHA-induced re-expression of LIFR and activation of downstream JAK1/STAT3 pathway." (PMID 34595180, 2021). "From the results in this research, EGFL6 regulates STAT3, FAK and Src, which correlate to cancer stem cell proliferation and self-renewal." (PMID 33726836, 2021). "Previously, we reported that (E)-N-(5-benzylthiazol-2-yl)-3-(furan-2-yl) acrylamide (aminothiazole, ATZ-502) showed cytotoxic effects in several cancer cells by blocking the function of KPNB1 with pSTAT3, STAT3, EGFR, and ErbB2." (PMID 33801927, 2021). "DHA potentiates the anti-cancer effects through a complementary reduction in phosphorylated EGFR, STAT3 and CAMKII proteins." (PMID 34829591, 2021). "Thanks to IL-6 autocrine and paracrine stimulus, CAFs upregulate VEGF, activate the JAK2/STAT3 pathway, express MCP-1, CCL11/8/20, CXCL5 and IL-9 for cancer cell invasion, growth and survival." (PMID 34944856, 2021). "In summary, we designed and manufactured a novel cancer nanovaccine named SVMAV that simultaneously loaded antigenic peptides, the TLR7/8 agonist R848 and the small molecule STAT3 inhibitor stattic." (PMID 34452929, 2021).
cancer (continued). "We also measured cellular GSH and found that MDA‐MB‐231 STAT3 KO cells had ~ 50% lower amounts of cellular GSH, as observed previously in other cancer cells." (PMID 33605027, 2021). "STAT3, a member of the STAT family of transcription factors, is considered as an oncogene activated in several cancers, including HNSCC." (PMID 33718169, 2021). "Similar to strong TNFR2 expression, strong STAT3 expression was found in 15 patients (60%) with FIGO stage III and stage IV cancer." (PMID 33809542, 2021). "STAT3 most likely takes part in CTCL progression, as its constitutive expression in advanced stages of this cancer has been observed." (PMID 32270320, 2021). "A common characteristic of many cancers, including PDAC, is the persistent phosphorylation of STAT3 on Tyr705, which mediates the nuclear translocation and functionality of STAT3 as a transcription factor." (PMID 34491463, 2021). "Later studies found that STAT3 activates miR-21 and miR-181b-1 through PTEN and CYLD as part of an epigenetic switch that links inflammation to cancer." (PMID 34956174, 2021). "Due to EMT-related transcription factors (SNAI1/2 and TWIST1) being the targets of STAT3, the activation of JAK/STAT3 signaling in cancer cells is commonly believed to initiate the EMT." (PMID 34298665, 2021). "We describe how this K-Ras/AGT/Ang II pathway induces senescence in normal cells while fuels cell transformation in cancer cells through the differential coupling of the AT1-R to NOX2 and STAT3 signaling, respectively." (PMID 33380422, 2021). "Considering STAT3 was closely related to immune cells in BLCA, KICH, and PRAD, so that we chose the three cancer types to investigate the correlation between STAT3 expression and the marker genes of immune cells." (PMID 32486001, 2020). "Aberrant signal transducer and activator of transcription 3 (STAT3) signaling promotes the initiation and progression of cancer in humans by either inhibiting apoptosis or inducing cell proliferation, angiogenesis, invasion, and metastasis." (PMID 33040485, 2020). "Among them, IL-6 and IL-11 are secreted interleukins activating STAT-3-dependent survival and spreading of metastatic CRC cancer cells." (PMID 33553157, 2020). "In these cancer types, RES inhibits STAT3 Tyr70522, 23, 24, 25, 26 and STAT3S72723, 25 phosphorylation." (PMID 33040485, 2020). "Therefore, STAT3 may play an important role in immune infiltration and cancer clinical therapy." (PMID 32486001, 2020). "It is well-known that IL-6 drives many “hallmarks” of cancer through downstream activation of the Janus kinase/signal transducer and activator of transcription 3 (JAK/STAT3) signaling pathway." (PMID 32373541, 2020). "At the transcription level, despite of being unexclusive, previous reports have shown that multiple transcription factors such as HIF1α, STAT3, SREBP, and TFEB can be closely regulated by mTORC1 in cancers." (PMID 32234750, 2020). "STAT3, one of the STAT family members, is a transcription factor playing a vital role in pathological processes of cancer." (PMID 32863764, 2020). "MiR-135a is dysregulated in various cancers and regulates cancer cell proliferation and invasion via several signaling pathways, such as the MAPK and JAK2/STAT3 pathways." (PMID 32944391, 2020). "Our data demonstrating activation of STAT3/5 in BTC cells and in PBMCs suggest a dual role for Jak/STAT signalling in promoting cancer cell proliferation and MDSC expansion." (PMID 32747748, 2020). "Several pathways/mechanisms such as COX-2, Nrf2, poly-ADP-ribosylation, Hedgehog, Wnt, Plk1, STAT3, NF-κB, PI3 kinase, or epigenetic modulations are implied in the modulation of cancer proliferation." (PMID 33375383, 2020). "Our study revealed that Benz reduced STAT3, NF-κB, β-catenin, and CD326/EpCAM, which are cancer cell survival factors, as well as CSC/CIC markers, concomitant with the inhibition of a number of pro-tumorigenic malignancy events." (PMID 32102440, 2020).
cancer (continued). "A durable partial response to OPB-111077, a small-molecule STAT3 and oxidative phosphorylation inhibitor, has already been observed in a DLBCL patient in a recent Phase I study in advanced cancers." (PMID 32309216, 2020). "Altogether, these results suggest that mmu_circ_0000730 targets mmu-miR-466i-3p and promotes cancer progression by suppressing the oncogenic effects of SOX9, activating STAT3 and forming a mmu_circ_0000730/miRNAs/SOX9 axis." (PMID 32686598, 2020). "Signal transducer and activator of transcription 3 (STAT3), a transcriptional factor involved in tumorigenesis and cancer stemness formation, contributes to drug resistance in cancer therapies." (PMID 33023006, 2020). "In fact, relationship between STAT3 and EMT not only is beneficial for invasion of cancer cells, but can also trigger chemoresistance." (PMID 32784711, 2020). "Natural products are capable of suppressing the migration of cancer cells by EMT inhibition via down-regulation of upstream molecular pathways, such as Snail and STAT3." (PMID 32992587, 2020). "The lncRNA LINC01535 reduces the sensitivity of cancer cells to apoptosis and enhances their growth through the induction of the JAK/STAT3 signaling pathway." (PMID 32545648, 2020). "Due to the increased activation of their stimulators, STATs are commonly constitutively active in disease and elevated activation of STAT3, STAT5A, STAT5B and in some cases STAT1, has been observed in most cancer types." (PMID 32915198, 2020). "Deregulation of STAT3/STAT5 activity was shown to be important for CTCL pathogenesis and cancer progression." (PMID 31963765, 2020). "Blocking these proteins also interferes with STAT3/STAT5-mediated transcription and cancer cell growth." (PMID 31963765, 2020). "The IL-6/JAK2/STAT3 pathway was discovered to be constitutively activated in human CRC and significantly related to cancer cell proliferation, invasion, and migration." (PMID 32518521, 2020). "Although STAT3 is a downstream target of PTEN, STAT3 also reversely inhibits PTEN expression by directly activating miR‐21, which is part of the epigenetic switch linking inflammation to cancer." (PMID 33448640, 2020). "Gene silencing of HIF-1α, the oxygen-sensitive subunit of the heterodimeric transcription factor HIF-1 (HIF-1α/HIF-1β), suppresses the phosphorylation of STAT3 in fibroblasts, while ouabain reduces HIF-1α levels in cancer and smooth muscle cells." (PMID 33101052, 2020). "HER3 promoted the activation of signal transducer and activator of transcription 3 (STAT3) resulting in upregulation of the STAT3 target gene SRY-Box Transcription Factor 2 (SOX2) and survival of the cancer cells." (PMID 33327495, 2020). "Signal transducer and activator of transcription 3 (STAT3) is an important transcription factor for control of many processes in immunity and cancer." (PMID 32863208, 2020). "In cancer cells, MUC1-C is upregulated by auto-inductive circuits resulting from interactions with proinflammatory TFs, such as NF-κB p65 and STAT3, which are activated by stress and drive the EMT program." (PMID 31953400, 2020). "Several signaling pathways, including IL‐6/JAK2/STAT3 and TGF‐β/Smad, as well as the crosstalk between them, contributed to EMT and cancer stemness." (PMID 31860165, 2020). "Due to their key roles in cancer development and progression, COX-2 and STAT3 have become attractive targets for the development of novel cancer therapeutics." (PMID 33299414, 2020). "STAT3, one of most studied STAT proteins, is continually activated in a wide range of tumors and involved in different steps of cancer progression, including proliferation, apoptosis, maintenance of cancer stemness, and metastasis." (PMID 32358527, 2020). "The activation of MDSC-derived STAT3 and NOTCH is closely related to cancer stemness and consequent cancer progression." (PMID 33091036, 2020). "CD109 was involved in the tumorigenesis and progression of various cancers via TGF-β1 signalling and STAT3 activation." (PMID 32507856, 2020).
cancer (continued). "The EGFR/HER2 signaling network is pivotal in controlling cancer proliferation and metastasis through the downstream effectors of AKT, ERK, and STAT3." (PMID 32143669, 2020). "Although long-term AZD9291 treatment reduced TRIB3 and EGFR expression, it upregulated the expression and phosphorylation of STAT3, STAT5, and ERK1/2, suggesting the compensatory activation of other oncogenic pathways and induction of cancer stemness." (PMID 32694521, 2020). "Our results indicated that STAT3 regulates MLST8 gene expression and facilitates the formation of mTORC1/2, cooperating with the mTOR pathway in cancer cell proliferation." (PMID 32495998, 2020). "During the progression of cancer, hyperactivation of JAK2/STAT3 signaling results in a poor prognosis." (PMID 32518521, 2020). "and their active ingredients (e.g., cordycepin, salidroside, and gallic acid) have been reported to possess anticancer activity by targeting some apoptosis pathways in cancer, such as Bcl-2/Bax, caspases, PI3K/Akt, JAK2/STAT3, MAPK, and AMPK." (PMID 32774302, 2020). "We previously showed that inhibition of STAT3 and ERK1/2 activation plays an important role in antiproliferation in cancer cells." (PMID 32630719, 2020). "In detail, the activity of NF-YA, STAT3, TCF4 and WT1 isoforms in cancers has been documented and proposed for cancer molecular stratification." (PMID 32244895, 2020). "It has also been shown that CBP/P300 complexes with cancer stem cell markers such as CD44 and STAT3 in the nucleus elicit STAT3 acetylation at Lys685, promoting subsequent STAT3 dimerization and cyclin D1 expression." (PMID 33003453, 2020). "DNA JB4 inhibits Src phosphorylation by direct binding to the SH3 domain of c-Src and suppresses invasion of cancer by disrupting the interaction between Src and Src-downstream targets such as EGFR, FAK, and STAT3." (PMID 31952344, 2020). "STAT3, JAK1, and MYC are three oncogenes that have both anti-apoptotic and proliferative effects on cancer cells." (PMID 33391626, 2020). "Similar to STAT3, STAT5B has been mostly reported to play a major role in the progression and pathogenesis of cancer, but expression and phosphorylation levels of STAT5B were not affected by TCN." (PMID 32422984, 2020). "Signal transducer and activator of transcription 3 (STAT3) generally participates in development and progression of human cancers." (PMID 31956373, 2020). "Here, FZD2, which induced STAT3 activation, induced the migration and invasion of ESCC cancer cells, and a high level of FZD2 expression predicted a poor prognosis for patients with ESCC." (PMID 32766155, 2020). "Although signal transducer and activator of transcription 3 (STAT3) and mTOR pathways play crucial roles in tumorigenesis, studies are underway to investigate cross‐talk between the two pathways in cancer cells." (PMID 32495998, 2020). "The new Pt(II) complex bearing 1,2,5-oxadiazole selectively interacted with STAT3 over STAT1 and displayed good antitumor activity in in vivo cancer model." (PMID 32967366, 2020). "Common molecular markers reported for the identification of cancer stem cell population are CD44, CD133, CD24, ABCB5, Lin28a, ALDH, phosphorylated STAT3, Nanog, Orail1 and OCT4, C-Met." (PMID 35047986, 2020). "These two inhibitors show the most potential among STAT3 SH2 domain inhibitors to date, based on preclinical studies that describe antitumor ability against various cancers." (PMID 32872659, 2020). "STAT3 and PLK1 are known to control each other's transcription in a positive feedback loop resulting in cancer cell survival, proliferation and resistance to apoptosis." (PMID 32231398, 2020). "We demonstrated that SNX-2112 inhibited cancer cell proliferation, decreased ABCB1 and ABCG2 gene expression levels and reduced the colony formation capacity of ECSLCs, which was enhanced by STAT3 silencing." (PMID 33390934, 2020).